SNORA61 (small nucleolar RNA, H/ACA box 61)
Synonyms: ACA61
Gene: Small nucleolar RNA gene on chromosome 1 (28,579,764 to 28,579,893, reverse strand). Ensembl gene ENSG00000278274.
Gene Ontology:
Biological process: RNA processing
Cellular component: nucleolus
Homologues: Orthologues: chimpanzee SNORA61 (100% identical), macaque SNORA61 (98% identical), rabbit SNORA61 (85% identical), guinea pig SNORA61 (82% identical), pig SNORA61 (82% identical).
Diseases named in the same sentence as SNORA61 in open-access papers:
SNORA61 is named in the same sentence as 1 disease in open-access papers, as found by Europe PMC text mining. Sharing a sentence is not in itself a finding about the gene and the disease.
SNORA61 shares sentences with these, for which no sentence is quoted: cancer (1 paper).